BRCA2 (BRCA2 DNA repair associated)
Diseases named in the same sentence as BRCA2 in open-access papers (continued):
Sharing a sentence is not in itself a finding about the gene and the disease.
cancer (continued). "BRCA2 is associated with multiple primary tumours including breast, colorectal, ovarian and other cancers." (PMID 16721370, 2006). "Compared to the population controls, the OR for intraductal cancer given a (heterozygous) form of BRCA2 variant was 2.5 (p = 0.0005; 95% CI: 1.5–4.1)." (PMID 16280055, 2005). "In a logistic regression analysis comparing BRCA2-associated cancers with non-BRCA1/2 cancers and taking into account age, grade and all tested histological and immunohistochemical factors, the only independently significant factor was age (P = 0.0001)." (PMID 15642173, 2005). "This study shows that CPM significantly reduces the risk for contralateral cancer among BRCA1 or BRCA2 mutation carriers." (PMID 16052221, 2005). "In our study, all patients carried the most common, easily detectable mutations of BRCA1 or BRCA2 that prevail in this region and can be associated with early onset cancer." (PMID 16168118, 2005). "When compared with familial non-BRCA1/2 cancers, the BRCA2-associated cancers were diagnosed at a younger age (median age 47 years; among non-BRCA1/2 patients the median age was 55 years; P ≤ 0.0005)." (PMID 15642173, 2005). "Two recent reports demonstrated that BRCA1 and BRCA2-associated tumors have distinct expression profiles in both breast and ovarian cancers." (PMID 15383145, 2004). "Genes involved in DNA repair, especially those that interact with the product of the BRCA1 or BRCA2 genes, are of particular interest as cancer risk modifiers in BRCA1/2 mutation carriers." (PMID 15138485, 2004). "Our study permits to estimate the prevalence of BRCA1 and BRCA2 mutations in a Belgian patient population referred to a family cancer clinic." (PMID 15026808, 2004). "As to the question of how cancer arises in cells with deficiencies in BRCA1 or BRCA2, it seems likely that the impaired function of HR is a key step, since this is the only established defect in BRCA2-deficient cells." (PMID 15054444, 2004). "It is of special interest to examine possible modifying effects of different polymorphism on cancer risk in BRCA2 carriers in the Icelandic population." (PMID 12644832, 2003). "Four cases showed concordant loss of BRCA1 alleles in left and right cancers, four for BRCA2, seven for ATM and four cases for FHIT, suggesting possible roles for these tumour suppressor genes." (PMID 12771912, 2003). "We have previously reported the results of mutation analysis of BRCA1 and BRCA2 cancer predisposition genes in a cohort of radiation-hypersensitive cancer patients." (PMID 12698192, 2003). "The higher frequency of alteration of FRA3B and reduced expression of Fhit in BRCA2-linked cancers was consistent with the idea that loss of BRCA2 function affects stability of the FRA3B/FHIT locus." (PMID 12771912, 2003). "Recently it has been shown that not only breast and ovarian but also other cancers are over-represented in BRCA2 linked families." (PMID 12373604, 2002). "Mutations in BRCA1 and BRCA2 genes are observed in breast, ovarian, and other cancers." (PMID 41741471, 2026). "Mutations in DNA repair genes such as BRCA2 may render these cancers susceptible to targeted treatments." (PMID 41472903, 2026). "Cancer patients with BRCA1 or BRCA2 germline mutations are sensitive to PARPi." (PMID 41510186, 2026). "Small molecule inhibitors of PARP are used to treat cancers with BRCA1 or BRCA2 mutations." (PMID 41326692, 2026). "These include cancers in patients with BRCA1 or BRCA2 mutations." (PMID 41537447, 2026). "These different mechanisms of pathogenesis may be combined, such as in case 4, which had both shared somatic mutations and a constitutional variant of BRCA2, which predisposes to cancer." (PMID 40404986, 2025). "Also, some studies found a higher risk of cancer with each pregnancy; meanwhile, other studies have observed that only BRCA2 increases the risk of cancer before 50 years." (PMID 39815370, 2025).
cancer (continued). "Additionally, a heterozygous pathogenic variant in BRCA2 was incidentally detected, associated with hereditary cancer predisposition." (PMID 41226549, 2025). "Additionally, nine (18.75%) survey takers tested positive for either BRCA1 or BRCA2 mutations, and 42 (87.5%) of patients’ cancers were hormone-positive." (PMID 41589155, 2025). "This is even more true because some of the predisposing variants may carry a risk for other cancers or diseases later in life, examples being mutations in BRCA2, STK11, BLM, and CDKN2A, among other genes." (PMID 40340749, 2025). "This approach encompasses the etiology, epidemiology, pathophysiology, screening, evaluation, and management of BRCA2 variants, and highlights the importance of an interprofessional team in educating patients about cancer risk and appropriate management strategies." (PMID 41283249, 2025). "Research shows BRCA1 and BRCA2 play vital roles not only in DNA repair and homologous recombination but also in germ cell development and function, potentially explaining how these mutations influence cancer risk." (PMID 41584579, 2025). "While BRCA2-associated cancers are predominantly hormone receptor-positive tumors, BRCA1-associated tumors are more frequently classified as triple-negative breast cancer (TNBC), a subtype known for its aggressive nature and higher sensitivity to neoadjuvant chemotherapy." (PMID 40422528, 2025). "Conversely, pathogenic variants in BRCA2 lack stability and are more likely to appear, but they may also be more prone to elimination due to a comparable cancer incidence between males and females." (PMID 40249378, 2025). "The increased incidence of double-stranded DNA damage observed in both biopsies and PDGOs from BRCA1 and BRCA2 carriers is particularly concerning, as this type of damage is the most severe form of DNA damage and thought to be a general risk factor for cancer development." (PMID 41256354, 2025). "Utilizing a cancer-related panel of 30 genes associated with hereditary PCa risk in 1351 patients (78% EA men), it was shown that most prevalent P/LP variants were in the BRCA2, CHEK2, MUTYH, and ATM DDR genes." (PMID 40002276, 2025). "Hence, aberrations within the HRR pathway, particularly germline or somatic deleterious mutations in Breast cancer gene-1 (BRCA1) BRCA1 or Breast cancer gene-2(BRCA2), can result in synthetic lethality in the presence of PARP inhibitors." (PMID 39333696, 2025). "Repeat CT and PET scans every 6 months may help in identifying new metastasis in time for intervention, especially in a BRCA2+ patient at higher risk of developing several types of cancers due to a germline mutation." (PMID 40225096, 2025). "Since BRCA2 mutations impair DNA repair mechanisms, telomere shortening may play a particularly critical role in increasing the risk of cancer progression in patients with this genetic predisposition." (PMID 40061142, 2025). "The BRCA2 P/LP variant carrier status was associated with a higher risk of cancers including PCa." (PMID 40002276, 2025). "The risk for BRCA2‐associated cancers should be evaluated in combination with cancer‐specific PGS." (PMID 40462315, 2025). "Importantly, we find that the loss of EP300 results in decreased expression of BRCA2 protein leading to sensitivity to treatments that are cytotoxic to BRCA-deficient cancers." (PMID 41354653, 2025).
cancer (continued). "Using these samples, we mapped and characterized the pattern of DNA DSBs or “breakome”, and analyzed how specific BRCA1 or BRCA2 mutations may impact early mammary carcinogenesis, and ultimately could play a role in early cancer detection." (PMID 41350536, 2025). "A recent study analyzed germline exomes from two MM cohorts (895 and 786 individuals) revealed that MM patients are more likely than healthy individuals to carry pathogenic germline variants (PGVs) in BRCA1 (OR = 3.9) and BRCA2 (OR = 7.0) genes, which significantly increase cancer risk." (PMID 40047910, 2025). "Prophylactic mastectomy is a risk-reducing surgical procedure performed to reduce the risk of developing cancer in the other breast in patients with a family history of cancer, known genetic mutations such as BRCA1 or BRCA2, or who have been diagnosed with cancer in one breast." (PMID 39830622, 2025). "Notably, the patient's cancer continued to respond to olaparib even after developing the BRCA2 reversion mutation." (PMID 40124187, 2025). "We report a rare case of this cancer in a patient with a germline BRCA2 (gBRCA2) mutation." (PMID 40091949, 2025). "Nevertheless, a higher rate of BRCA2 mutations in men compared to women may be associated with more aggressive cancers and thus a reduced survival rate." (PMID 40824530, 2025). "In contrast, a varied pattern was observed in BRCA2, with four out of the eight pathogenic variants being significantly more frequently detected in the regional cohort compared to the nationwide cancer cohort, and a similar tendency was observed for five of the 12 VUS variants." (PMID 40249378, 2025). "When utilized effectively, genetic testing for cancer risk-increasing mutations, (such as pathogenic mutations in the BRCA1 and BRCA2 genes) can identify high-risk individuals prior to cancer development, allowing for tailored interventions aimed at early cancer detection and prevention." (PMID 40862808, 2025). "In this context, it is noteworthy that observations in large cohorts have shown that individual FA-associated BRCA2 PVs may have an organ-specific cancer signature." (PMID 40724944, 2025). "Of note, while increasing evidence points to ssDNA gaps as the initial DNA lesion that sensitizes cancer cells to PARPi, work from the Jasin laboratory has recently suggested that, at least in a BRCA2-mutant setting, loss of HR is the ‘ultimate’ cause of sensitization to PARPi." (PMID 39927794, 2025). "Finally, we illustrated the need to incorporate PGS in estimating penetrance for all BRCA2‐associated cancers." (PMID 40462315, 2025). "This may be attributed to the higher penetrance of APC mutations and the earlier onset age of FAP compared to cancers associated with BRCA2." (PMID 39985003, 2025). "Some apparently sporadic cancers in the pediatric population may also be associated with monoallelic BRCA2 PV carrier status." (PMID 40724944, 2025). "Association of BRCA2 PVs with cancers beyond core HBOC syndromes remains controversial." (PMID 40462315, 2025). "Of the 71 patients with CFTR PVs, two patients had PV in other genes with either an established or possible association with increased cancer risk consisting of the L2357 frameshift variant in BRCA2 (rs80359636) and the Y179C missense variant in MUTYH (rs34612342)." (PMID 41147257, 2025). "This discrepancy in regional distribution between BRCA1 and BRCA2 variants could be attributed to factors such as the diversity of the genome, gender differences, and cancer types." (PMID 40249378, 2025). "Importantly, while BRCA1-mutated, BRCA2-mutated, and WT triple-negative tumors showed high rates of pCR, the frequency of NACT failure (i.e., RCB III) was similar between HR+ BRCA2-associated and WT cancers." (PMID 40547808, 2025).
cancer (continued). "However, in terms of age, the group carrying BRCA1 and BRCA2 co-mutations had a significantly earlier age of cancer onset than the rest patients (mean age, 51 VS 54.5 years, Wilcoxon test P value 7.30e-03)." (PMID 38817903, 2024). "The BRCA1 and BRCA2 mutations lead to malignant tumors in the breast, ovary, and pancreas." (PMID 38730578, 2024). "Thus, BRCA1 and BRCA2 are recognized as tumor suppressors, and their loss serves as an enabling hallmark of cancer by increasing genomic instability." (PMID 39198848, 2024). "In addition, testing for high-penetrance genes beyond BRCA1 and BRCA2 should be offered to those with a family history, and, if necessary, for moderate-penetrance genes when coupled to personal and family cancer risk information." (PMID 38491334, 2024). "Therefore, to understand BRCA2 tumorigenesis and potential synthetic lethal targets, it is crucial to reveal the mechanisms underlying the paradox that BRCA2 depletion causes cancer but also leads to the lethality of individuals and normal cells." (PMID 37934606, 2024). "BRCA1 and BRCA2 gene analyses are the most commonly performed tests used to determine the inheritance of breast cancer and are usually recommended for patients at high risk of cancer and their relatives, especially if there is a family history of cancer." (PMID 38753118, 2024). "So, one idea that our recent findings raise is that metabolic changes implicated in cancer risk, or that occur during carcinogenesis, can temporarily bypass Knudson's two-hit requirement for BRCA2, provoking genome-wide mutation patterns implicated in carcinogenesis." (PMID 39711301, 2024). "Therefore, PP2Ai, which can reactivate the SAC, can kill BRCA2-deficient tumor cells very effectively, making it a potential therapeutic drug for cancer patients with BRCA2 mutations." (PMID 37934606, 2024). "In addition, more efforts should be encouraged on further categorizing the pathogenicity of VUS, such as the recurrent BRCA2 c.8971 C > T in the cancer cohort and the potential splicing abnormalities causing BRCA1 c.548-15G > A in the healthy group." (PMID 38566028, 2024). "And loss of PARG, induced olaparib resistance in BRCA1- or BRCA2-deleted cancer cells." (PMID 38625917, 2024). "Therefore, it is possible that unsampled areas of the primary tumor contained cancer of higher grade clonally related to the MMR-proficient BRCA2-deficient clone." (PMID 39623053, 2024). "We also used Cas9 to directly test the function of individual amino acids, including amino acids encoded by clinical BRCA2 variants of uncertain significance, and identified alleles that are sensitive to PARP inhibitors used as a standard of care in BRCA2-deficient cancers." (PMID 37488236, 2024). "Together with previous results, these findings further suggest that haploinsufficiency of PALB2 or BRCA2 can be a potential initiating event for malignant changes in these heterozygous cell models, and possibly also in cancers associated with such disease predisposition." (PMID 38597967, 2024). "Individuals even in families carrying the same germline BRCA2 mutation exhibit differences in their age of cancer onset and the type of cancers they may develop, speaking to the existence of modifiers of cancer risk." (PMID 39711301, 2024). "Michalak and Kang (2018) highlighted a unique and likely pathogenic divergence of the BRCA2 in Homo neanderthalensis relative to other primates, including modern humans, raising a question about cancer susceptibility in the archaic species that were replaced by modern humans 40,000 years ago." (PMID 38338903, 2024). "Based on these studies, we propose that targeting PP2A to reactivate the SAC may be a promising strategy for treating cancer patients with BRCA2 mutations." (PMID 37934606, 2024).
cancer (continued). "In work published earlier this year, we have been able to show that an aldehyde byproduct of glycolysis, methylglyoxal, can inactivate BRCA2 by protein degradation, triggering genome-wide patterns of single-base substitution mutations that are implicated in cancer initiation." (PMID 39711301, 2024). "BRCA1/BRCA2, established tumor suppressors, have been observed paradoxically to inhibit cellular proliferation, which has been difficult to reconcile with their known cancer predisposition phenotype." (PMID 39198848, 2024). "It is suggested that polymorphisms in the BRCA2 gene may affect the function of the protein and its expression, which also increase the risk of cancer." (PMID 38892180, 2024). "The role of BRCA2 in cancer susceptibility is poorly understood." (PMID 37934606, 2024). "However, cooperating events that facilitate the transition of BRCA2 mutation–containing cells to cancers typically prevail; their identity and mechanisms of action are slowly emerging." (PMID 38557488, 2024). "For BRCA2, 16 distinct variants in the association of cancer were identified in 17 individuals." (PMID 39148954, 2024). "If BRCA2 p.I3169M fs*48 variant had some DNA repair capabilities, cancers with this variant might be insensitive to platinum or PARP inhibitors." (PMID 37956396, 2024). "Research is aiming to establish whether cancers occurring in individuals at high genetic risk (eg, BRCA2 carriers, those with high polygenic risk scores) are more aggressive than those in people with no detectable genetic predisposition." (PMID 38583453, 2024). "PP2A is an attractive synthetic lethal therapeutic target for BRCA2-mutated cancer." (PMID 37934606, 2024). "How replication-fork dynamics in the context of BRCA2 deficiency influences the location and enrichment of TRCs, and whether locus-specific TRCs impact genomic instability and cancer development remains ill-defined." (PMID 38830843, 2024). "While BRCA2 mutations contribute to genomic instability and malignant transformation, previous studies have found that the BRCA2 gene can inhibit the occurrence and development of cancer." (PMID 39073402, 2024). "However, there was a significant aggregation of PLP variants in the BRC repeats (P = 0.019) and DNA binding domain (P = 0.015) of BRCA2 in cancer patients, whereas in healthy individuals, PLP variants were scattered across functional domains." (PMID 38566028, 2024). "BRCA1 mutation carriers have an actual greater cancer risk than BRCA2 mutation carriers." (PMID 39192282, 2024). "PARP is an enzyme involved in DNA transcription and repair, and its inhibition is useful to treat tumors with mutations in BRCA1 (breast cancer gene 1) and BRCA2 (breast cancer gene 2) and other genes involved in the repair of homologous recombination deficits." (PMID 38965194, 2024). "Overall, BRCA2 has been associated with a more heterogeneous cancer spectrum, compared with BRCA1." (PMID 38339330, 2024). "Mainly, women were treated for a Stage I cancer (52.6%) and carried a BRCA2 (57.9%) mutation." (PMID 38192174, 2024). "This suggests that PALB2 and BRCA2 may be associated to similar carcinoma risks because BRCA2 needs PALB2 to be recruited in the HR repair." (PMID 38672070, 2024). "In cancers with BRCA1/BRCA2 mutations or other defects in HR repair, cells are dependent on poly-adenosyl-ribose polymerase (PARP) enzymes to carry repair of their damaged DNA and are thus prone to apoptosis if the enzyme is inhibited by PARP inhibitors, a concept known as synthetic lethality." (PMID 36975505, 2023). "These assays examine the ability of BRCA1 and BRCA2 variants to support cell viability, sensitivity to DNA damaging agents, ability to repair DSBs by HR, or to exhibit transcriptional activity and predict the role of mutations in cancer-predisposition." (PMID 37713444, 2023). "BRCA1 and BRCA2, discovered in 1990s, are known cancer predisposition genes." (PMID 37020472, 2023).